ULK1 (unc-51 like autophagy activating kinase 1)
Diseases named in the same sentence as ULK1 in open-access papers (continued):
Sharing a sentence is not in itself a finding about the gene and the disease.
gastric cancer (continued). "Ulk1 over-expression was also observed in several gastric cancer cell lines (AGS, HGC-27, and SNU601)." (PMID 28410240, 2017). "In addition, PCA significantly suppressed the growth of gastric cancer in the gastric cancer xenograft mouse model by activating key proteins related to the AMPK/ULK1 signaling pathway of autophagy." (PMID 40260299, 2025). "ULK1 protein levels can also be regulated by transcription and phosphorylation: phosphorylation at Ser556 activates ULK1 to promote autophagy, demonstrating a tumor-suppressive effect in gastric cancer." (PMID 39218913, 2024). "Mechanistically, AQP5 regulated the autophagy and stemness of gastric cancer stem cells by recruiting E3 ligase Tripartite Motif Family Like 1 (TRIM21) to the key autophagy protein Unc-51 Like Autophagy Activating Kinase 1 (ULK1) and inducing the ubiquitination of ULK1." (PMID 37681902, 2023). "MiR-1262 adds a new layer of ULK1 regulation in gastric cancer." (PMID 33442421, 2021). "We explored the activation of AMPKα and ULK1 in DSGOST-mediated gastric cancer cells." (PMID 29844404, 2018). "Next, we tested expression of Ulk1 in human gastric cancer cells." (PMID 28410240, 2017). "Together, we demonstrate that Ulk1 over-expression in human gastric cancer is pro-survival." (PMID 28410240, 2017). "Meanwhile, Ulk1 over-expression was also noticed in several gastric cancer cell lines." (PMID 28410240, 2017). "Here, we tested expression and potential function of Ulk1 in human gastric cancer." (PMID 28410240, 2017). "Importantly, high Ulk1 expression in gastric cancer was significantly correlated with patients’ T classification and cancer relapse." (PMID 28410240, 2017). "These in vitro and in vivo evidences suggest that over-expressed Ulk1 could be an important oncotarget protein for human gastric cancer." (PMID 28410240, 2017). "Together, these results demonstrate Ulk1 over-expression in fresh human gastric cancer tissues." (PMID 28410240, 2017). "We first tested expression of Ulk1 in human gastric cancer specimens." (PMID 28410240, 2017). "Ulk1 mRNA and protein were significantly elevated in multiple fresh human gastric cancer tissues." (PMID 28410240, 2017). "Importantly, high Ulk1 expression in gastric cancer was correlated with patients’ T classification and cancer relapse." (PMID 28410240, 2017). "In addition, TMEM87A could promote metastasis of gastric cancer and cell proliferation by elevating ULK1 via sponging miR-142-5p29." (PMID 38886500, 2024). "However, contradictory findings suggest that ULK1 may suppress cancer development and metastasis in breast and gastric cancers." (PMID 39218913, 2024). "Similarly, ULK-1 was shown to be a favorable prognostic marker in gastric cancer." (PMID 28696368, 2017). "The m6A modification of its downstream gene ULK1 can be removed by FTO, thus protecting it from targeted degradation by YTHDF2 and playing a role in cisplatin resistance in gastric cancer (GC)." (PMID 39468015, 2024). "It has been shown that Unc-51-like kinase 1 (ULK1) expression was regulated in an FTO-m6A-dependent and YTHDF2-mediated manner in gastric cancer." (PMID 36246528, 2022). "The knockdown of ULK1 induced a decrease of cell viability and an increase of LDH release in DSGOST-treated gastric cancer cells." (PMID 29844404, 2018). "In support of this, we observed significantly negative expression correlation between ULK1 mRNA and miR-1262 in gastric cancer tissues." (PMID 33442421, 2021). "Furthermore, the ULK1 knockdown cells decreased LC3B level and slightly reduced p62 level in DSGOST-treated gastric cancer cells compared with the control cells." (PMID 29844404, 2018). "Pharmacological interference of ULK1 and PRKAA2 as therapeutic targets might provide a novel therapeutic strategy to target gastric cancer cells, which are resistant to cisplatin/5-FU treatment." (PMID 28109268, 2017).
gastric cancer (continued). "Therefore, using western blotting, we investigated whether the AMPKα/ULK1 and mTOR/p70S6K pathways were involved in DSGOST-induced autophagy in gastric cancer cells." (PMID 29844404, 2018).
lung carcinoma (28 papers, 2017 to 2025). "ULK1 kinase stability or its phosphorylation status determines its involvement in autophagy regulation or mitophagy towards cancer progression; ULK1 was identified to be associated with the poor prognosis of patients with lung cancer." (PMID 36927870, 2023). "When the copper transporter CTR1 or ULK1 is genetically lost or mutated, copper binding is disrupted, which lowers ULK1/2-dependent signaling, autophagosome complex formation, and lung cancer development and survival." (PMID 36553481, 2022). "Up to now, ULK1 as a potential target for autophagy activity regulation has been reported in a large amount of the literature, and ULK1 inhibitors have been reported to function in lung cancer cells, FLT3‐ITD‐mutated acute myeloid leukemia and neuroblastoma." (PMID 33040463, 2020). "Interestingly, we found that ARHGs with active copy number increase (e.g. MYC, EIF4EBP1, EGFR) and ARHGs with active copy number loss (e.g. ATG16L1, MTOR, ULK1) also showed high expression in lung cancer tissues." (PMID 35333893, 2022). "CLDN1 was also shown to be a potent factor promoting lung cancer resistance to cisplatin, which was achieved by activating autophagy through the upregulation of Unc-51-like autophagy activating kinase 1 (ULK1) phosphorylation." (PMID 40943068, 2025). "This study has become the basis for the interest in combination therapies using cycloastragenol and inhibiting the AMPK/ULK1/mTOR pathway in lung cancer cells." (PMID 40362333, 2025). "More recently, CK1δ and ε have been shown to play an important role in ULK1-mediated autophagy in lung cancer and melanoma cells by regulation of ULK1 levels." (PMID 39001502, 2024). "ULK1 was recently identified as an oncogene that suppressed antitumor immune response in lung cancer." (PMID 36475797, 2022). "Taken together, these results showed that BHGJT induced autophagy via the AMPK/mTORC1/ULK1 signaling pathway in lung cancer." (PMID 34659548, 2021). "Regarding the mechanism, the AKT/GSK3β/β-catenin signaling pathway was responsible for growth arrest and apoptosis induced by BHGJT, and activation of autophagy was attributed to the AMPK/mTORC1/ULK1 signaling pathway in lung cancer cells." (PMID 34659548, 2021). "For example, a suppressed translation and degradation of ULK1 represents a potential mechanism for autophagy limitation in lung cancer, whereas miR-320c was described as core predictor for lung and other cancers." (PMID 29981854, 2018). "Consequently, these data suggest that ULK1/2-mediated autophagy is a pharmacologically actionable cytoprotective stress response to inhibition of KRASG12C in lung cancer." (PMID 39213022, 2024). "In closing, our data support the testing of ULK1/2 inhibitors in patients with KRAS-driven lung cancer, either as single agents or in combination with direct inhibitors of KRAS oncoproteins, or of KRAS-regulated signaling pathways downstream of KRAS such as the RAF>MEK>ERK MAP kinase pathway." (PMID 39213022, 2024). "Unc-51 like autophagy activating kinase 1 (ULK1), a key regulator of autophagy in lung cancer cells, is methylated by overexpressed PRMT5, enhancing the autophagic process and improving the survival rate of lung cancer cells under hypoxic conditions, promoting resistance to carboplatin." (PMID 38525426, 2024). "In the lung tissues of NSCLC patients, LC3B expression was reduced, whereas the levels of p62, ULK1 and ATG5 were significantly increased, indicating that enhanced autophagy may be associated with the deterioration of lung cancer." (PMID 35379783, 2022). "In lung cancer, it was reported that miR-106a can negatively regulate ULK1 by inhibiting autophagy." (PMID 33572255, 2021).
lung carcinoma (continued). "Additionally, autophagy was induced by BHGJT via the AMPK/mTORC1/ULK1 signaling pathway, and blocking autophagy with either chloroquine or a ULK1 inhibitor increased the killing efficiency of BHGJT in lung cancer cells." (PMID 34659548, 2021). "In lung cancer, claudin-1 is a key factor responsible for resistance to cisplatin, which is accomplished by activating autophagy via the upregulation of Unc-51-like autophagy activating kinase 1 (ULK1) phosphorylation." (PMID 34354941, 2021). "miR-106a suppresses ULK1 expression and thereby sensitizes lung cancer cells to Src-TKI treatment." (PMID 33505399, 2020). "In lung cancer, claudin-1 is a key deciding factor for metastasis and a responsible factor for drug resistance towards cisplatin through the up-regulation of Unc-51 Like Autophagy Activating Kinase 1 (ULK1) phosphorylation." (PMID 31861759, 2019). "Hence, this work supports the hypothesis that patients with KRASG12C-driven lung cancers may benefit from treatment with the combination of KRASG12C plus ULK1/2 inhibitors." (PMID 39213022, 2024). "Furthermore, it was reported that lung cancer-associated lncRNA 1 (LCAL1) was overexpressed in lung cancer tissues, which suppressed autophagic cell death, supporting cancer cell survival and proliferation by deactivating the AMPK/ULK1 signalling pathway." (PMID 35379783, 2022). "In this study, we found that targeting USP24 by USP24-i-101 can dramatically induce autophagy through upregulation of ULK1, LC3 and ULK phosphorylation at Ser555 in lung cancer to negatively regulate drug resistance." (PMID 38491202, 2024). "In lung cancer, CLDN1 expression was reported to promote the chemotherapeutic resistance of NSCLC through ULK1 phosphorylation, but methylation of the CLDN1 gene can enhance the efficacy of chemotherapy to inhibit the progress of LUAD." (PMID 36193204, 2022). "We also found that BHGJT induced marked autophagy through the AMPK/mTORC1/ULK1 signaling pathway and that blockade of autophagy further improved the efficiency of BHGJT in lung cancer cells." (PMID 34659548, 2021). "CDDP-resistant H460 and H1975 lung cancer cells showed increased levels of the mTORC1-dependent ULK1S757 phosphorylation, which prevents ULK1 activation by AMPK10." (PMID 32943635, 2020). "Beyond lung cancer, knockdown of GGH could result in the activation of the ULK1 complex and PI3KC3-C1 via the phosphorylation of ULK1 and PIK3C3 in a multitude of cancer cell lines." (PMID 40268350, 2025). "Moreover, the combination of DCC-3116, a selective ULK1/2 inhibitor, plus sotorasib displays cooperative/synergistic suppression of human KRASG12C-driven lung cancer cell proliferation in vitro and superior tumor control in vivo." (PMID 39213022, 2024). "In another study, bis-indole derivatives of 1-methoxyspirobrassinol methyl ether induced autophagy in A549 (lung carcinoma epithelial cells) by modulation of the phosphorylation or expression of various autophagy markers, such as Beclin-1, AMPK, ULK1, p62, Atg7, and LC3A/B." (PMID 38675591, 2024). "Human KRASG12C-driven lung cancer cells are sensitive to co-inhibition of KRASG12C and ULK1/2." (PMID 39213022, 2024). "Additionally, we revealed that protective autophagy was obviously induced by BHGJT via the AMPK/mTORC1/ULK1 signaling pathway and that inhibiting autophagy by CQ or MRT68921 facilitated cell death upon treatment with BHGJT in lung cancer." (PMID 34659548, 2021). "Indeed, we did observe that DCC-3116 treatment modestly inhibited the growth of one human KRASG12C mutant lung cancer cell line, NCI-H358, both in vitro and in vivo, suggesting that ULK1/2 inhibition as a monotherapy may indeed have significant single-agent activity in certain settings." (PMID 39213022, 2024). "Combined, but not individual, treatment of lung cancer cells strongly increased the phosphorylation of eIF2α S51, ATG13 S318, JNK and p38 whereas it decreased the phosphorylation of AKT T308, p70 S6K T389, mTOR S2448 and ULK-1 S757." (PMID 27903966, 2017).
glioma (26 papers, 2013 to 2026). A benign or malignant brain and spinal cord tumor that arises from glial cells (astrocytes, oligodendrocytes, ependymal cells). "We hope that the phosphorylation antibodies of these three sites of ULK1 would be applied to the detection of ULK1 activity in the clinic, which is expected to become a diagnostic index for glioma resistance." (PMID 31378785, 2019). "N25 induces autophagy in glioma cells through a new mechanism of upregulating Tip60 by inhibiting HDAC3, causing upregulation of ULK1 (Atg1) and Beclin-1 (Atg6), and resulting in induction of glioma cell autophagy." (PMID 29088860, 2017). "Studies have suggested that low expression of ULK2 might be associated with its promoter hypermethylation, causing autophagy by ULK1/ULK2 for glioma progression." (PMID 39348350, 2024). "We then explore whether hirudin‐induced autophagy in glioma cells is associated with the activity of the mTOR signalling pathway by detecting the phosphorylation levels of ULK1, P70S6K, and 4EBP1, which are the core proteins of the mTOR signalling pathway." (PMID 37539490, 2023). "Therefore, we proposed a hypothesis that N25 induces autophagy probably through a new mechanism of upregulating Tip60 by inhibiting HDAC3, causing upregulation of ULK1 (Atg1) and Beclin-1 (Atg6), and resulting in induction of glioma cell autophagy." (PMID 29088860, 2017). "It interacts with ULK1 and inhibits autophagy by phosphorylating ULK1 at Ser469, Ser495, and Ser533, thereby contributes to glioma resistance to temozolomide (TMZ)." (PMID 41362722, 2026). "Overexpression of H19 promotes the proliferation and migration of glioma cells, and H19 promotes the proliferation and autophagy of glioma cells through the mTOR/Unc-51-like autophagy-activating kinase 1 (ULK1) pathway." (PMID 38481525, 2024). "Autophagy: H19 overexpression suppressed autophagy of glioma cells via regulating the mammalian target of rapamycin (mTOR)/Unc-51 like autophagy activating kinase 1 (ULK1) axis by inducing increased ULK1 phosphorylation and inhibiting mTOR phosphorylation." (PMID 34322395, 2021). "The phosphorylation of ULK1 decreases the activity and stability of ULK1, thus, inhibiting autophagy and promoting resistance against temozolomide in glioma cells." (PMID 32033142, 2020). "The phosphorylation of these three sites of ULK1 plays an important role in the resistance of gliomas to TMZ." (PMID 31378785, 2019). "Our study showed that TOPK interacted with the SPR domain of ULK1 and phosphorylated Ser469, Ser495, and Ser533 of ULK1, reducing the activity and stability of ULK1, thus inhibiting autophagy, and promoting glioma resistance to TMZ." (PMID 31378785, 2019). "Nevertheless, N25 inhibited HDAC3 and up-regulated the protein expression of Tip60, ULK1, and Beclin-1 in glioma cells." (PMID 29088860, 2017). "Nevertheless, N25 inhibited HDAC3 and up-regulated the protein expression of Tip60, ULK1 (Atg1), and Beclin-1 (Atg6) after treatment of glioma cells with N25." (PMID 29088860, 2017). "We additionally analyzed the protein expression level of HDAC3, Tip60, ULK1 (Atg1), and Beclin-1 (Atg6) after treatment with N25 in glioma cells." (PMID 29088860, 2017). "In contrast, starved and AZD 8055-treated control MEFs and U87-MG glioma cell lysates showed dephosphorylation of Ser-757 or a corresponding shift in the mobility of total ULK1, consistent with an mTOR-mediated response." (PMID 23762328, 2013). "Moreover, T-LAK cell-originated protein kinase (TOPK) inhibits autophagy by phosphorylating ULK1 in glioma cells and promotes glioma resistance to TMZ." (PMID 34671362, 2021). "Overall, the data indicate that TOPK decreases ULK1 activity and stability in glioma cells." (PMID 31378785, 2019). "The results indicated that TOPK decreases ULK1 activity in glioma cells." (PMID 31378785, 2019). "Huh-7 (DENV, YFV) or human glioma NCE U373 (TBEV) cells were pre-treated with 3 mM ASA/SA, 100 μM AMPK, or ULK1 activators for 2 h prior to infection." (PMID 40072063, 2025).
glioma (continued). "A weak positive correlation of miR-21 was observed with AKT (rs = 0.38) and LC3 correlated positively with PTEN (rs = 0.47), ULK1(rs = 0.45), VPS34 (rs = 0.48) in high-grade glioma." (PMID 39348350, 2024). "For example, autophagy-related genes, including ULK1, ATG10, and ATG16L2, possess a prognostic value in glioma cohorts and were used as the biomarkers in diagnosing glioma." (PMID 37182147, 2023). "Further study showed that hirudin caused a decrease in the phosphorylation of mTOR and its downstream factors ULK1, P70S6K and 4EBP1 and preliminarily showed an inhibitory effect of hirudin on glioma via cell‐derived xenografts (CDXs) in nude mice in vivo." (PMID 37539490, 2023). "In glioma, autophagy induces TMZ resistance but phosphorylation of ULK1 by T-LAK cell-originated protein kinase (TOPK), an upstream oncokinase, reduced autophagy and increased sensitivity of glioma cells to TMZ." (PMID 35877430, 2022). "On the other hand, it has been demonstrated that berberine induced autophagy in glioma cells through the activation of AMPK, with subsequent inactivation of mTOR and an increase in the levels of phosphorylated ULK1." (PMID 30486451, 2018). "In 39 glioma cases, we assessed the protein expression of autophagy markers LC3B, SQSTM1/p62, and DRAM by immunohistochemistry (IHC) and the mRNA expression of the autophagy genes PTEN, PI3K, AKT, mTOR, ULK1, ULK2, UVRAG, Beclin 1, and VPS34 using RT-qPCR." (PMID 38203743, 2024). "AKT positively correlated with LC3, PI3K, PTEN, ULK1, VPS34, mTOR, Beclin1, UVRAG, miR-7, miR-30, miR-204, miR-374, miR-126 and miR-21 weakly correlated with AKT and miR-30 in high-grade glioma, providing further insights into the autophagy pathway within our population." (PMID 39348350, 2024). "Mechanistically, hirudin activated LC3‐II but not Caspase‐3 to induce the autophagic death of glioma cells by decreasing the phosphorylation of mTOR and its downstream substrates ULK1, P70S6K and 4EBP1." (PMID 37539490, 2023). "We observed that the selective knockdown of ULK1, Atg5, or Atg7 or pharmacological inhibition of autophagy with 3MA increased the levels of active caspase 3, 7 and PARP degradation in WIN55,212-2-treated LN18 glioma cells." (PMID 33499365, 2021). "In grade 3 gliomas, a significant, strong, positive correlation was observed between PI3K and mTOR, ULK2, UVRAG; mTOR and PTEN; PTEN and m-TOR, ULK 2, UVRAG; mTOR and PI3K, PTEN; ULK1 and ULK2, UVRAG; ULK 2 and PI3K, PTEN, ULK 1, UVRAG, VPS34; UVRAG and PI3K, PTEN, ULK1, ULK2, VPS34." (PMID 38203743, 2024). "Inhibition of ULK1 restored radiosensitivity in human IDH-mutant but not IDH-wildtype glioma." (PMID 35877430, 2022).